INHBA (inhibin subunit beta A)
Diseases named in the same sentence as INHBA in open-access papers (continued):
Sharing a sentence is not in itself a finding about the gene and the disease.
tumor (continued). "A study conducted by Grunberg suggested that HSF1 upregulated inhibin subunit beta A (INHBA) and thrombospondin 2 (THBS2), which are involved in tumor progression." (PMID 34064083, 2021). "A cluster of genes that were upregulated in the tumours, compared to normal tissues were COL1A1, COL11A1, SPP1, COMP, SFRP4 and INHBA." (PMID 34824625, 2021). "The expression levels of PHTF2, MFAP2, INHBA, TSPAN9, and CCL26 (p < 0.05) displayed tumor stage-dependent alterations." (PMID 34456964, 2021). "The expression of STC2, ESM1, INHBA, CXCL1 and TDGF1 was significantly increased in tumor tissues than in normal tissues, whereas GLP2R expression was higher in normal tissues than in tumor tissues." (PMID 32788867, 2020). "We then performed qRT-PCR in SFE-treated ESCC cells and ground tumor lumps from the previous xenograft tumor assay, verifying that the expression of CXCL10, TNFAIP3, INHBA, and PLAU was indeed controlled by SFE in ESCC." (PMID 33374641, 2020). "When these mice (HPV8/wt mice) were mated with transgenic mice overexpressing INHBA in keratinocytes (wt/Act mice), HPV8‐induced tumor formation was strongly accelerated." (PMID 32150356, 2020). "Genes such as INHBA, IGF2, LGALS1, RHOJ, and THBS2 were upregulated in the tumor buds but downregulated in the microenvironment." (PMID 28687755, 2017). "Immunohistochemistry showed high expression of INHBA and NEK6 proteins in 14 of 20 and 24 of 27 tumour tissues, respectively, whereas IGFBP7 and LUM proteins showed little immunoreactivity in tumour tissue relative to adjacent healthy tissue (data not shown)." (PMID 18827816, 2008). "Importantly, we show that INHBA maintains mitochondrial SLC25A10 stability, thereby activating the succinate/SUCNR1 axis and the mtGSH/GPX4 axis to promote tumor malignancy." (PMID 41449244, 2025). "Also, we identified novel predicted tumor-suppressive ligands (SLIT3, DCN, CCN3, THBS1, INHA and INHBA), proteins (DNASE1L3, SULF1, PTEN, OAS1, and DAB2IP), and receptors (P2RX4, CDHR2, PTPRJ, and PTPRH) in MSC1 cells." (PMID 40564222, 2025). "Additionally, the TCGA database indicated significantly higher expression of CLDN1 and INHBA, while CXCL12 displayed lower expression between COAD tumor and control samples, consistent with our analysis results of the DEGs, DEMs, and DMRs." (PMID 40426863, 2025). "CLDN1 and INHBA are consistently over-expressed in COAD and are associated with poor prognosis and tumor progression, suggesting their potential role as negative prognostic biomarkers." (PMID 40426863, 2025). "INHBA, the highest overexpressed gene in the HPV-negative tumor, was knocked down." (PMID 38329386, 2024). "The results showed that the levels of INHBA in PanNEN tumor tissues were significantly higher compared with adjacent normal tissues." (PMID 38252148, 2024). "Interestingly, the transcriptomic analysis showed that the spheroid co-culturing, compared to separate mono-cultures of HT-29 and fibroblasts, induced upregulation of INHBA, SerpinA1 and S100A9, which are well-known players in tumor biology." (PMID 39011470, 2024). "In addition, except for TIMP1 (P > 0.05), the expression levels of INHBA (P < 0.05), LAMC2 (P < 0.05), PLAU (P < 0.05) and TGFβ1 (P < 0.05) were significantly different between tumour and normal samples." (PMID 37325056, 2023). "ECM factors such as periostin, INHBA, MMPs and TGF‐β produced by POSTN+ CAFs could shape the stromal milieu in favour of immune exclusion and tumour growth." (PMID 38115703, 2023). "These include CTHRC1, INHBA, BGN, and PDPN, all of which are known to promote tumor progression." (PMID 38036590, 2023). "Finally, we verified that the expression levels of KLF9, MCM2, INHBA, and CGREF1 were related to age, tumor stage, and differentiation and were closely related to the prognosis of young CRC patients." (PMID 37370046, 2023).
tumor (continued). "INHBA and LCN2 were downregulated in this study, which implied that INHBA and LCN2 may play crucial roles in tumor recurrence in HCC patients after LT." (PMID 37089051, 2023). "INHBA+ TAM and monocytes were located in a single branch in the dendrogram, implying that this cluster probably was originated from infiltrated monocytes in tumor regions." (PMID 35664061, 2022). "In addition, subcutaneous xenograft nude mouse models confirmed that the growth of tumours was weakened by knock‐down MMP14 and INHBA." (PMID 35150061, 2022). "ssGSEA analysis also associated both these macrophage subsets with alterations in several pathways related to carcinoma progression, T cell exhaustion, cell migration, sprouting angiogenesis, and wound healing, in agreement with tumor supportive roles reported for NLRP3 and INHBA." (PMID 36439171, 2022). "Of interest, INHBA expression was negatively correlated with infiltrating levels of activated NK cells, NKT, and CD4+ T cells but was positively correlated with tumor infiltration of CD8+ T cells, neutrophils, especially macrophages and cancer-associated fibroblasts." (PMID 36304286, 2022). "Other significant DE genes with high FC(log2), unique to the study were INHBA, COL1A1, COL11A1, COMP, SFRP4 and SPP1, which were clustered in STRING network analysis and correlated with tumour-infiltrating immune cells in TIMER, suggesting a specific interaction pathway." (PMID 34824625, 2021). "Moreover, significant differences were found in the expressions of INHBA, CCL26, MFAP2, TSPAN9, and PHTF2 in tumor stage based on TCGA-ESCA, suggesting their prognostic value in ESCC tumor development." (PMID 34456964, 2021). "Ectopic expression of INHBA in DLBCL cell lines (OCI-Ly01 and SUDHL-10) resulted in reduced cell proliferation, increased spontaneous apoptosis and, an arrested cell cycle and suppressed xenograft tumor growth." (PMID 29225711, 2017). "Among them, INHBA and RECQL4 were frequently overexpressed and amplified in various tumor types." (PMID 28377632, 2017). "In this study, somewhat surprisingly the expression of INHBA and also the protein level were not downregulated in the majority of tumour-adjacent and HCC samples studied, but even increased in several HCC." (PMID 21407220, 2011). "This is consistent with the apparent lack of expression of INHA in the normal and tumor tissues of all three patients and implicates INHBA as a potential oncogene in OSCC." (PMID 20174472, 2010). "INHBA expression is elevated within EOC, with gene expression correlating with worse survival and activin protein levels correlating with specific immune infiltration that may lead to suppressing anti‐tumor immunity in EOC." (PMID 39248018, 2024). "However, despite the tendency for the level of DNA methylation in the promoter region of INHBA to be lower in tumor tissue compared to normal tissue, this difference did not achieve statistical significance." (PMID 39543755, 2024). "Furthermore, INHBA exhibited a negative correlation with the level of tumor-infiltrating B cells, which have a controversial role in cancer." (PMID 38329386, 2024). "Given that CAFs are reported to be an important stromal component and are critically involved in tumor progression, we reclustered the CAFs and further categorized them into two main types: inflammatory CAFs (iCAFs; CFD, CKB, and DPT) and myoblastic CAFs (myCAFs; INHBA, SULF1, and COL8A1)." (PMID 36725337, 2023). "Notably, we found that KLF9 and INHBA were associated with prognosis in EOCRC but not in LOCRC, while the expression differences in KLF9, MCM2, and INHBA between the tumor and normal groups were more obvious in EOCRC than in LOCRC." (PMID 37370046, 2023). "Since INHBA/activins proteins are multifunctional ligands and their superfamily member, TGF-β, is closely involved in angiogenesis, INHBA may also play a role in tumor angiogenesis." (PMID 35058963, 2021).
tumor (continued). "Since INHBA/activins proteins are multi-functional ligands and its superfamily member, TGF-β, is closely involved in angiogenesis, we speculated that the overexpression of INHBA may have some role in tumour biology." (PMID 21897392, 2011). "Thus reduced expression of INHBA, β subunit of activin A, in UOK257 cells and BHD tumors, may be permissive for tumor cell growth." (PMID 20573232, 2010). "Therefore, we sought to further verify whether the expression level of INHBA in tumor tissues was higher than that in non-tumor tissues." (PMID 35216189, 2022). "Similarly, the INHBA+ macrophage subset co-expressed pro-tumorigenic molecules such as IL6, TGFβ, TIMP1, CCL20, CXCL1, and IL10, highlighting the highly plastic and complex nature of tumor-infiltrating myeloid cells in vivo, consistent with recent similar studies in other solid tumors." (PMID 36439171, 2022). "We explored the potential for activin in tumor establishment and growth in vivo via CT26 cells with/without siRNA for INHBA." (PMID 37296966, 2023). "Other clinicopathological factors included tumor size, differentiation, TNM stage, and vascular and nerve invasion; INHBA levels did not shown statistic differences." (PMID 35909892, 2022). "Although GDC-0919 alone or in combination with anti-PDL1 neither show antitumor activity nor affect tumor immune cell infiltration, GDC-0919 was found to induce downregulation of granzyme expression, as well as upregulation of inhibin subunit beta A (inhba) and E3 Ubiquitin ligase Dtx4." (PMID 38433193, 2024). "The levels of anti-tumor immune-response-related factors (interferon-γ (IFN-γ), interleukin-10 (IL-10), tumor necrosis factor- α (TNF-α) and IL-2) were evaluated in patients with negative and positive expressions of INHBA." (PMID 36984496, 2023).
cancer (116 papers, 2007 to 2025). A tumor composed of atypical neoplastic, often pleomorphic cells that invade other tissues. "Cluster3 expressed the TGF β coactivator INHBA, which was significantly associated with prognosis in several types of cancer, highlighting the potential prognostic value of Cluster3 in cancer." (PMID 38648200, 2024). "Stress can also impact stromal components, stimulating the secretion of inhibin-βA (INHBA) from cancer cells and activating cancer-associated fibroblasts, leading to collagen deposition and extracellular matrix (ECM) formation." (PMID 38831236, 2024). "The association between INHBA's participation in cancer and activin A levels has been found in the oesophagus, prostate and ovarian malignancies." (PMID 39656597, 2024). "Intriguingly, this transcript has been previously associated with cancer progression, thanks to INHBA up-regulation." (PMID 38528259, 2024). "In this study, by exploiting original murine orthotropic cancer models as well as human lung cancer specimens, we first showed the critical pathogenic function of lung AMs expressing activin A/INHBA as an inducer of cancer progression." (PMID 36650150, 2023). "We discovered unique and novel features of the gastric TME, including an increased proportion of plasma cells in diffuse-type tumors, and a role for INHBA, a subunit of activin–inhibin complexes, in specific subtypes of cancer-associated fibroblasts (CAF)." (PMID 34642171, 2022). "The high levels of INHBA promoted cancer invasion and metastasis and were associated with poor survival of patients." (PMID 36304286, 2022). "We observed increased plasma cell proportions in diffuse-type tumors associated with epithelial-resident KLF2 and stage-wise accrual of cancer-associated fibroblast subpopulations marked by high INHBA and FAP coexpression." (PMID 34642171, 2022). "We also uncovered distinct cancer-associated fibroblast subtypes with INHBA–FAP-high cell populations as predictors of poor clinical prognosis." (PMID 34642171, 2022). "Further, ssGSEA analysis associated NLRP3+ and INHBA+ macrophage subsets with multiple pathways related to carcinoma, angiogenesis, wound healing, and T cell exhaustion; all classical hallmarks of efferocytosis." (PMID 36439171, 2022). "Inhibin-βA (INHBA), a ligand belonging to the transforming growth factor-β superfamily, is associated with cell proliferation in cancer." (PMID 33828156, 2021). "INHBA or MSTN expression is associated with several types of human cancers, and CRC patients with high INHBA expression showed poorer OS than those with low INHBA expression." (PMID 32970737, 2020). "Our laboratory has previously shown that INHBA encodes for an autocrine factor required for cancer stem-cell like properties." (PMID 30885209, 2019). "Similarly, we observe differential expression of INHBA in cluster 3, a senescence mediator that’s associated with prognosis in many cancer types." (PMID 38221640, 2024). "Likewise, INHBA is upregulated in all three cancer subtypes and its upregulation is associated with poor survival in triple‐negative breast cancer." (PMID 38708713, 2024). "Thus, we analyzed the methylation data by focusing on those involved in growth and identified INHBA as the most significant gene associated with cancer progression in UTUC." (PMID 35216189, 2022). "Moreover, INHBA expression showed strong correlations with various markers of monocytes/macrophages and cancer-associated fibroblasts." (PMID 36304286, 2022). "INHBA rs2237432 is reported to have a significant association with fertility, although the clinical significance in cancer remains unknown." (PMID 32970737, 2020). "The expression level of TGFB/INHBA and other invasion-associated genes was measured by quantitative-PCR (Q-PCR) and Western Blot after transfection/treatments with clones/reagents in normal/cancer cells." (PMID 26298390, 2015).
cancer (continued). "Moreover, Kaplan-Meier analyses of OS based on INHBA expression and immune cell infiltration demonstrated that high INHBA expression, along with infiltration of cancer-associated fibroblasts, granulocyte-monocyte progenitors, macrophages, and M2 macrophages were associated with a worse prognosis." (PMID 39543755, 2024). "Notably, this included TGF-β (TGFB1, TGFB3), drivers of adenosine-mediated immune suppression (NT5E (CD73), ENTPD1 (CD39)), Wnt pathway ligands (WNT7A, WNT4), IL10 and drivers/markers of cancer-associated fibroblast activation (INHBA, WNT7A, TGFB1, FAP, PDGFRA, PDGFRB)." (PMID 39568014, 2024). "INHBA is a widely expressed transforming growth factor-beta family member, which is a biomarker for some cancers." (PMID 40563693, 2025). "Upon treatment with small-interfering RNA targeting INHBA, cancer cell proliferation decreased and improved the therapeutic effects of radiation therapy." (PMID 41463203, 2025). "Upregulated hub genes BGN and INHBA exhibited reduced methylation levels, possibly contributing to their overexpression in cancer." (PMID 40898538, 2025). "INHBA is involved in cellular senescence and immune evasion, and it promotes cell proliferation and metastasis in several cancers." (PMID 40563693, 2025). "INHA and INHBA, inhibit activin signaling by competing for activin receptor binding, thereby reducing proliferation in cancer cells." (PMID 40564222, 2025). "The RCC score includes a panel of 12 genes, with 7 cancer-related genes (stromal genes: INHBA, BGN, and cell cycle genes: MKI67, MYC, MYBL2, GADD45B) and 5 reference genes, and is used to predict CRC recurrence." (PMID 40664638, 2025). "Dysregulation of the INHBA gene induces metastasis and keeps mesenchymal phenotypes in cancer cells." (PMID 39003454, 2024). "Together, the data thus confirm that both BMP7 and INHBA are expressed in different cancer subtypes and are likely to play a role in their progression." (PMID 38708713, 2024). "It is likely that cancer cells are responsible for the induction of INHBA expression in CAFs as INHBA(+) CAFs were observed only in proximity to cancer cells." (PMID 38360876, 2024). "To further investigate the impact of INHBA expression on chemosensitivity, we assessed the effect of INHBA expression on drug sensitivity using the Genomics of Drug Sensitivity in Cancer (GDSC) database." (PMID 39543755, 2024). "Over the past few decades, there has been a gradual investigation into the involvement of INHBA in different malignant tumours." (PMID 39656597, 2024). "Although INHBA is seldomly expressed in epithelial cancer cell lines, the majority of cancer-related research on INHBA has utilized rare epithelial cancer cell lines that express INHBA or cancer cell lines in which INHBA was ectopically overexpressed." (PMID 38360876, 2024). "Emerging evidence has demonstrated that INHBA serves important roles in a wide variety of cancer progressions." (PMID 38252148, 2024). "More recently, a new mechanism was proposed wherein INHBA-expressing cancer cells activate CAFs, which in turn promotes cancer progression." (PMID 38360876, 2024). "Cancer-associated fibroblasts (CAF) expressed well-known markers including FAP, COL1A1, COL10A1, MMP11, and CTHRC120,21, and other genes such as INHBA, SLC12A8, F2R, and COL12A1 in various organs." (PMID 38744958, 2024). "The upregulation of VCAN mediated by INHBA can promote the migration and proliferation of cancer cells in CRC." (PMID 38730335, 2024). "More CD163+ INHBA+ macrophages were observed in the alveolar cavities of cancer tissues than in normal lung tissues." (PMID 36650150, 2023). "INHBA is a member of the transforming growth factor-β superfamily and regulates a number of cellular events, including regulation of cancer cell growth and metastasis, apoptosis and, primarily, proliferation and differentiation of human embryonic stem cells." (PMID 36735680, 2023).